ATG5 (autophagy related 5)
Diseases named in the same sentence as ATG5 in open-access papers (continued):
Sharing a sentence is not in itself a finding about the gene and the disease.
infection (continued). "Furthermore, the pathogen Sphingomonas paucimobilis, which is exquisitely sensitive to NKT cell mediated immune control during early infection, reached lower bacterial loads associated with higher cytokine production in the absence of Atg5 in dendritic cells and some macrophages." (PMID 30542350, 2018). "Of these molecules, RIG-I, MDA5, ATG5, SOCS1, SOCS3, INF-a, ISG15and ISG56 showed differences in expression levels at different time points after DENV-3 or DENV-3 ADE infection." (PMID 29566761, 2018). "Consistently, Atg5-Atg12 conjugation and LC3 lipidation were visible after infection with replication-competent R124 at an MOI of 10 or UV-inactivated R124 at an MOI* of 200 and 1000." (PMID 28934149, 2017). "Collectively, these results revealed that knockdown of the endogenous ATG5 and LC3B genes increased the infection of PRV." (PMID 28059118, 2017). "The frequency of LC3-positive P. acnes in Raw264.7, Atg5+/+ MEF, Atg5-/- MEF, and HeLa cells at 8 h postinfection was compared in the same experiment among different conditions of P. acnes used for infection." (PMID 27219015, 2016). "A significant decrease in intracellular viral RNA synthesis was detected in two mutant strains of K562 carrying homozygous deletions of ATG5 after DENV and DENV-ADE infection." (PMID 26923481, 2016). "A stronger interaction of RIG-I and IPS-1 with ATG5 protein was observed in trehalose-treated cells, especially with HRV-16 infection." (PMID 25879848, 2015). "Nevertheless, the conversion of rBCV to aBCV at a later stage of infection, i.e. 48 h and 72 h p.i., seems to be dependent on ULK-1, Beclin1, Atg14L and hVps34 but independent on Atg5, Atg7, Atg16L1 and Atg4B." (PMID 25179110, 2014). "During the early stages of infection, NS5B of HCV interacts with ATG5 and stimulates the conjugation of LC3 to PE." (PMID 24710493, 2012). "Then we evaluated virulent F. tularensis SchuS4 infection of THP-1 cells in which six top hit genes (TNFRSF9, SERPINI1, HLA-DBR1, PLEK2, ATG5 and ATG16L1) were knocked down by individual lentiviral shRNA." (PMID 22359626, 2012). "This notion is supported by evidence showing that intracellular infection with Francisella down-regulates several autophagy-related genes in THP-1 human monocytes, including ATG5, ATG12, ATG16L2, ATG7, ATG4A and class III PI3K." (PMID 20003180, 2009). "Infection of C. parvum leads to up-regulation of Beclin-1, ATG7, and ATG5." (PMID 40681213, 2025). "Mice lacking ATG5 in LYZ2+ cells are extremely susceptible to Mtb infection and succumb to Mtb infection by 40 days post-infection, similar to a mouse lacking IFN-γ signaling." (PMID 40910070, 2025). "Moreover, cells were also transfected with ATG5-specific siRNA or a control sequence for 24 h, or treated with 5 mM 3-Methyladenine (3-MA) for 6 h, followed by GCRV infection." (PMID 40454785, 2025). "Similar to atg5 CRISPants, the triple knockdown did not affect the survival of larvae upon infection." (PMID 40987772, 2025). "Infection with C. albicans has been reported to induce increased expression of autophagy markers LC3, ATG5, and LAMP1, and study also showed that apoptosis and necrosis was reduced in human vaginal epithelial cells overexpressed with wild-type ATG5." (PMID 40727105, 2025). "Infection with S. uberis induced (p < 0.01) Nrf2, HO-1, IL-6, TNF-α and Atg5." (PMID 38397769, 2024). "The expression of ATG5, ATG7, ATG12, and LC3 in BMDMs was remarkably enhanced after both BCG and H37Rv infection." (PMID 38016969, 2023). "Moreover, conditional ablation of Atg5 or Atg7 in peripheral blood-derived CD8+ T cells (also known as cytotoxic T lymphocytes) induces defective autophagy flux, pathogen infection, and survival defects in memory T cells." (PMID 37180758, 2023). "We assume that the 12-h infection time was not sufficient to elicit a significant difference in ATG5 expression." (PMID 37740192, 2023).
infection (continued). "A morpholino knockdown demonstrated that embryo survival, and recruitment of LC3 to vacuoles following infection, required ATG5 but did not require ATG13, a component of the ULK1 complex required to initiate canonical autophagy." (PMID 36288298, 2022). "Thus, ATG5 and ATG7 core autophagy factors were involved in the augmented lipidation of LC3 observed during the DUGV infection of Huh7 cells." (PMID 36298785, 2022). "There were no marked changes noted in the expression of Becn1, Atg5, Atg7, Atg12, Atg16l1 or Atg16l2 both before and 6 h after infection." (PMID 35903351, 2022). "The mRNA expression of other ATG genes in WT, such as the mRNA expression of ATG4a and ATG4b decreased and then rise; the mRNA expression of ATG5 and ATG12a decreased with the infection time of AvrRpt2 (data not shown); these are very interesting." (PMID 32708160, 2020). "As expected, ATG5-downregulated cells failed to accumulate LC3-II during starvation or Ngo infection." (PMID 30753248, 2019). "R. australis promotes the accumulation of Atg5-dependent LC3 but does not actively induce an autophagic flux in primary mouse macrophages at the very early stage of infection." (PMID 30297526, 2019). "To confirm that low levels of autophagy were not required for IAV replication, we infected Atg5–/– MEFs, showing that autophagy is indeed dispensable for infection." (PMID 29748576, 2018). "Moreover, DENV-ADE infection induced higher ATG5 and ATG12 transcription at very early stage (0.5 and 1 hours post-infection) compared to the DENV direct infection." (PMID 26923481, 2016). "Results showed that the similar reduction effect to Atg5 knockdown donors was observed in Atg9 knockdown donors (data not shown), suggesting the decreased infection rates are not due to the lower virus production of autophagy-deficient donor cells." (PMID 27558165, 2016). "In addition, we also have assessed the exogenous Atg5-IRGM and exogenous Atg10-IRGM interaction upon CA16 infection." (PMID 25853521, 2015). "Unlike atg5 and atg7 mutants, nbr1 mutants were normal in age- and dark-induced senescence and in response to necrotrophic pathogen infection." (PMID 23341779, 2013). "The effective knockdown of Atg5 was confirmed by qRT-PCR and we verified that atg5 silencing did not perturb cell differentiation and cell infection." (PMID 23272151, 2012). "Consistent with this, silencing Atg5 in MLE‐12 cells resulted in aggregated mitochondrial damage, as evidenced by a substantial decrease in mitochondrial membrane potential and a significant increase in the production of both total ROS and mtROS during PAO1 infection." (PMID 40529614, 2025). "Additionally, the levels of procaspase‐11 and cleaved caspase‐11 were elevated in mice lacking alveolar epithelial Atg5 compared to control mice following infection." (PMID 40529614, 2025). "Therefore, the observed decrease in infection in ATG5 KO cells is likely due to a non-canonical role of ATG5." (PMID 38915300, 2024). "Considering that this finding was not reproduced upon CytoD or Atg5 siRNA treatment, we excluded a role of either phagocytosis or autophagy, and we hypothesize that endocytosis could play a small role at early infection time points." (PMID 35899053, 2022). "However, H3K27me3 was not enriched at either Atg5 or Atg7 promoters under similar infection conditions." (PMID 34381738, 2021). "Interestingly, the expression levels of autophagy-related proteins of LC3II (P < 0.01) and Atg5 were definitely increased (P < 0.001), while SQSTM1 were significantly decreased (P < 0.05) following the infection with ALV-J or the overexpression of GADD45β for 4 h in DF-1 cells or CEF cells." (PMID 32826872, 2020). "On the contrary, another study showed a significant enhancement in progeny virus particle production at 24 and 48 hpi but not at 72 hpi following infection with WNV-NY99 at MOI 0.01 in Atg5−/− MEFs when compared to Atg5+/+ MEFs or Atg5−/− cells back-transfected with Atg5." (PMID 30862253, 2019).
infection (continued). "In our experiments, however, impaired autophagy was strikingly accompanied by decreased IL-12 secretion, which seems to contradict an earlier study reporting that mice lacking the autophagy protein Atg5 in myeloid cells secrete higher amounts of IL-12 in response to infection with Mtb." (PMID 29434592, 2018). "Interestingly, animals lacking ATG5, a key autophagy regulatory molecule, show massive inflammation and lung pathology upon infection with M. tuberculosis." (PMID 27303736, 2016). "Moreover, infection of mice lacking ATG5 with M. tuberculosis, a protein essential for the processing of LC3B, results in increased bacterial burdens and enhanced inflammatory responses in comparison to ATG5 expressing mice." (PMID 24528777, 2014). "Interestingly, although IFN β, IL6 and IP10 mRNA production are almost equivalent at 8 hours post-infection when comparing infected and non-infected cells, the levels were significantly higher in Atg5 and Atg7 knock-down cells relative to control cells." (PMID 23320079, 2013). "Deletion of ATG5 had no negative impact on SARS-CoV-2 RNA uptake, since the Cq values were comparable between the respective parental and ATG5KO cells at 2 h post-infection (open circles)." (PMID 40167317, 2025). "Infection with PV, DENV, or ZIKV also led to the formation of GFP–LC3 puncta in both the presence and absence of ATG5." (PMID 30608919, 2019). "As for the Atg5 and LC3 expression, acidic vesicles were detected in U251-MG upon Rapa treatment and jin-1 but not R124 infection, as expected." (PMID 28934149, 2017). "Huh7 infection by HCVpp was not altered in cells treated with siRNA against LC3, ATG7 or ATG12, thus suggesting that neither LC3 nor the ATG5-12 conjugate is involved in viral entry." (PMID 28067309, 2017). "Corresponding to this, altered Atg5 and LC3-II expression was observed upon Rapa treatment and jin-1 but not R124 infection." (PMID 28934149, 2017). "Silencing of LC3 impeded HCV only when performed before infection, thus suggesting that the ATG5-12 conjugate, but not LC3, is important in viral replication after the establishment of infection." (PMID 28067309, 2017). "The requirement of autophagy-initiation proteins ULK1, Beclin 1, and ATG14L and PI3-kinase activity but not elongation proteins ATG5, ATG16L1, ATG4B, ATG7, and LC3B suggested Brucella selectively co-opts autophagy-initiation complexes to subvert host clearance and promote infection." (PMID 38376367, 2024). "However, ARP101 treatment revealed a unique pattern in which both LC3 II and p62 were induced later during infection, and ARP101-induced LC3 II formation was independent of ATG5, suggesting the classical autophagy pathway was not required for ARP101 activity." (PMID 36939350, 2023). "Interestingly, by day 7 of infection, multiple genes were elevated in young H1N1 infected lung, such as Atg5, Mapk8, Tbk1, Casp8, and Ripk1, that were not similarly expressed in response to H3N2." (PMID 34829979, 2021). "Therefore, for B. abortus, the higher CFUs in Atg5−/− MEFs vs WT MEFs could be explained by an increase in the percentage of infected cells among the cell population or by a higher survival rate during the early times after infection rather than by a higher replication rate." (PMID 25179110, 2014). "However, previous work showed that autophagy may be beneficial for FMDV as virus yields were reduced in cells lacking ATG5, suggesting that FMDV induces autophagosomes during cell entry to facilitate infection." (PMID 28660175, 2017).
neurodegenerative disease (15 papers, 2008 to 2024). A disorder of the central nervous system characterized by gradual and progressive loss of neural tissue and neurologic function. "A variety of studies have showed that variants of ATG5 gene are related to certain diseases of the immune system and neurodegenerative diseases." (PMID 29326554, 2017). "Mice deficient in either Atg5 or Atg7 in the CNS develop progressive behavioral and motor deficits typically associated with neurodegenerative diseases." (PMID 26503303, 2015). "Except for ATG5 gene variants, the expression of plasma ATG5 could also characterize susceptibility to neurodegenerative diseases." (PMID 34661876, 2022). "Experimental evidence showed that down-regulation of autophagy-related genes, Atg5 or Atg7, in the CNS lead to the aggregation of poly-ubiquitinated protein debris in neurodegenerative disease animal models." (PMID 37181621, 2023). "In recent years, it has been found that the abnormal expression or gene deletion of ATG5 is closely related to the occurrence of a variety of neurodegenerative diseases." (PMID 34661876, 2022). "There is growing evidence that autophagy-related gene 5 (ATG5) is involved in neural development, neuronal differentiation, and neurodegenerative diseases." (PMID 34661876, 2022). "Inhibition of basal autophagy in vivo following Atg5 or Atg7 deletion results in the accumulation of ubiquitinated protein aggregates leading to cytotoxicity and neurodegenerative disease, highlighting the critical cytoprotective role of basal autophagy." (PMID 35968799, 2022). "Specific overexpression of certain proteins such as SIRT1, BIP, and/or ATG5 facilitates neuronal survival after nerve injury, and they neuroprotect in neurodegenerative diseases." (PMID 33578870, 2021). "Polymorphisms in the ATG genes, including ATG5 and ATG7, have been associated with an early onset of neurodegenerative diseases, including HD." (PMID 31941072, 2020). "ATG5 plays a key role in autophagosome formation and recent studies have shown a correlation between abnormal expression or gene deletion of ATG5 and the onset of several neurodegenerative diseases." (PMID 38933683, 2024). "To investigate the contribution of autophagy and mitophagy in degenerative diseases, we investigated the serum levels of specific autophagic markers (ATG5 protein) and mitophagic markers (Parkin protein) in a population of older patients by enzyme-linked immunosorbent assay." (PMID 31882960, 2019). "In the future, we will take ATG5 as the starting point to further study the molecular mechanism of PD pathogenesis, which may provide certain reference value for the diagnosis and treatment of neurodegenerative diseases related to ATG5 expression level to a certain extent." (PMID 34661876, 2022).
bacterial infection (9 papers, 2011 to 2025). "Our findings illustrate that R. australis exploits Atg5-mediated mechanisms to support bacterial infection in association with dampening of the IL-1β-mediated antirickettsial effect in macrophages." (PMID 30297526, 2019). "Further, ATG5 (KO) mice generated from Sftpc-cre mice and Atg5flox/flox mice were subjected to intranasal bacterial infection." (PMID 38264727, 2023). "NLRP3 and ATG5/ATG16L1-mediated autophagy signaling pathway plays an important role in regulating immune response to resist bacterial infections." (PMID 36362066, 2022). "In contrast, S. pneumoniae superinfection of IAV-infected MEF atg5-KO cells showed a significant decrease in bacterial intracellular survival compared to the bacterial infection only." (PMID 32790758, 2020). "Next, to examine whether VopQ-induced autophagy suppresses the NLRC4 inflammasome, we performed the short hairpin RNA (shRNA) knockdown of ATG5, one of the components of autophagy in NLRP3-deficient BMMs and assessed inflammasome activation upon bacterial infection." (PMID 23357873, 2013). "H3K9me2/3 was significantly enriched at the promoter regions of both Atg5 (P ≤ 0.01) and Atg7 (P ≤ 0.001) in response to MtbPrt bacterial infection, while no such enrichment was observed in uninfected and MsmpSMT3-infected cells." (PMID 34381738, 2021). "Future endeavors aimed at unraveling the molecular interactions involving ATG5, PINK1, Parkin, and PHB2, combined with more comprehensive functional assays, hold the potential to provide insights into the intricate role of ATG5 in mitophagy, particularly in the context of bacterial infections." (PMID 40529614, 2025).
adenocarcinoma (7 papers, 2015 to 2023). A common cancer characterized by the presence of malignant glandular cells. "To demonstrate the impact of autophagy in lung tumor cell expansion, we first compared gene expression in A549 adenocarcinoma cell lines in which autophagy genes (ATG5 or ULK1) had been deleted or not (GSE73158 dataset)." (PMID 35884522, 2022).
cardiovascular disease (6 papers, 2020 to 2025). "Among cardiovascular disease-relevant, differentially methylated genes in males, Atg5, Ank2, Cux1 and Lamp2 exhibited significant increases in gene expression." (PMID 33445541, 2021). "Furthermore, recent research analyzing macrophages extracted from blood samples of patients with cardiovascular disease has revealed significant downregulation of autophagy‐related genes LC3 and Atg5, accompanied by a marked increase in TNF‐α levels." (PMID 39508636, 2024). "By using both pharmacological and genetic approaches, including CRISPR-mediated knockout of ATG5 and ATG7, this study provides robust evidence that autophagy is a critical determinant of cholesterol homeostasis, offering new insights with potential therapeutic relevance for cardiovascular disease." (PMID 41343507, 2025).
benign tumors (5 papers, 2018 to 2022). "Experiments in mice with systemic mosaic deletion of Atg544 or liver-specific Atg5 knock-out28 reported the development of spontaneous benign tumors in the liver such as FNH as a result of the impairment of autophagy that led to oxidative DNA damage and hepatocyte proliferation." (PMID 35603298, 2022).
inflammation (5 papers, 2019 to 2022). Aberrant reaction of the microcirculation characterized by movement of fluid and leukocytes from the blood into extravascular tissues. "Particulate aerosols induce lung inflammation in mice that is enhanced by Mtor deficiency, and reduced when autophagy is inhibited by Atg5-deficiency, suggesting that increased autophagy contributes to lung inflammation in this model." (PMID 35608088, 2022). "Mice with autophagy deficiency (Atg5−/− and Atg7−/−) develop spontaneous sterile lung inflammation." (PMID 35057008, 2022). "Remarkably, adoptive transfer of Atg5−/− ILC2 cells attenuated IL-33-induced pulmonary inflammation and AHR, while autophagy activation in ILC2-specific TfebTG mice enhanced Th2 cytokine release, highlighting a central role for autophagy in the effector function and metabolic responses of ILC2s." (PMID 34204710, 2021).
neurological disorders (5 papers, 2019 to 2025). "Our preliminary observations assessing expression levels of ATG5, a crucial autophagy component, indicate no changes with age which contrast with the expected decline in aging-related neurological disorders." (PMID 37179123, 2023).
metabolic disorders (4 papers, 2015 to 2023). "The effects of autophagy deficiency on endMT were independent of the TGFβ pathway but IL-6-dependent: IL-6 neutralizing antibody prevented endMT in ATG5 knock-down human microvascular cells and ameliorated metabolic disorders in endothelial-selective ATG5 deficient mice fed with high fat diet." (PMID 36980288, 2023).
renal disease (4 papers, 2013 to 2025). "Consistently, studies in mouse models have demonstrated that reduced function of ULK1, ATG5 or ATG7 in kidney cells is closely associated with various kidney diseases, including DKD59,60." (PMID 41131336, 2025). "On the other hand, the analysis of clinical characteristics showed that high IL-10 producers carriers of the Atg5 T* allele presented significantly lower prevalence of cytopenia and a trend of less renal disorder compared with the other genotypes." (PMID 24205307, 2013).